FAAH (fatty acid amide hydrolase)
Diseases named in the same sentence as FAAH in open-access papers (continued):
Sharing a sentence is not in itself a finding about the gene and the disease.
migraine (continued). "Specifically, AEA levels were lower in the spinal fluid of patients with chronic headache such as migraine, and FAAH was suggested as a target for treatment in cases of AEA deficiency migraine." (PMID 35889535, 2022). "No clinical trials on compounds capable of modulating the ECS (such as FAAH/MAGL inhibitors) are currently available for migraine." (PMID 35329806, 2022). "The results indicate that the novel global FAAH inhibitors ARN14633 and ARN14280 elicit significant anti-hyperalgesic effects in a migraine-specific animal model and inhibit the associated peptidergic-inflammatory response." (PMID 35799128, 2022). "By contrast, all three compounds blocked FAAH activity and increased levels of FAAH substrates in the three migraine-related structures under study – medulla, cervical spinal cord, and trigeminal ganglia." (PMID 35799128, 2022). "Recent pharmacological studies have shown that inhibition of FAAH increases ECS activity and causes analgesia and reduces inflammation in animal models of migraine, but little is known about its effects in orofacial pain." (PMID 35563056, 2022). "The potentiality of increasing endocannabinoid system activity through inhibition of FAAH or MAGL has been tested in animal models of migraine." (PMID 34685523, 2021). "In this study, we showed for the first time, the comprehensive profile of activity and specific inhibition of endoCB-hydrolyzing enzymes MAGL and FAAH in tissues of origin and transmission of migraine pain." (PMID 33530477, 2021). "Taken together, our studies suggest a therapeutic potential of both endocannabinoids by dual FAAH/MAGL inhibition in migraine pain." (PMID 34685523, 2021). "Here, we tested the dual FAAH/MAGL inhibitor JZL195 in an animal model specific for migraine as a pharmacological probe to evaluate the impact of simultaneous inhibition of AEA and 2-AG degradation on the trigeminal system." (PMID 34685523, 2021). "Our findings highlight MAGL and FAAH as promising targets for novel anti-migraine strategies via selective enhancement of the anti-nociceptive endoCB drive in this common neurological disorder." (PMID 33530477, 2021). "In the CNS, both MAGL and FAAH represent potential targets for attenuation of migraine-related enhanced cortical excitability and pain transmission." (PMID 33530477, 2021). "The activity of MAGL was higher than the respective activity of FAAH not only in TG, but also in DRG and brainstem, which are also implicated in the transmission of migraine pain." (PMID 33530477, 2021). "Next, to identify additional molecular targets for analgesia by affecting the most active ECS enzymes, we investigated the activity of MAGL and FAAH in central areas involved in the generation and transmission of migraine pain." (PMID 33530477, 2021). "Conclusion - The findings confirm that inhibition of FAAH activity represents a promising target for modulating the pathways that are likely involved in migraine pain." (PMID 30238173, 2018). "In this review, we summarize results collected in studies aimed at evaluating the role of the endocannabinoids (ECs) in migraine, with a specific focus on fatty acid amide hydrolase (FAAH) inhibitors." (PMID 29615860, 2018). "Future experiments should be aimed at unlocking the precise cellular mechanisms and neural circuits through which peripheral FAAH blockade exerts its analgesic effects in migraine pain, further exploring the ground for potential clinical trials." (PMID 29615860, 2018). "Platelets of women with migraine showed increased activity of FAAH when compared with men with migraine." (PMID 28861505, 2017). "Female migraine sufferers had higher FAAH protein, suggesting lower endocannabinoid levels." (PMID 39118031, 2024). "FAAH gene expression was lower in the migraine groups compared to that in the controls." (PMID 36835524, 2023). "FAAH inhibitors are effective in animal models of inflammation and pain, including migraine." (PMID 37373250, 2023).
migraine (continued). "In particular, both brain permeant (e.g., URB597) and impermeant (e.g., URB937) inhibitors of FAAH produce similar pharmacological effects in animal models of migraine on nociceptive tests, including the tail flick test as well as the orofacial and plantar formalin test." (PMID 37373250, 2023). "In an animal model of nitroglycerin-induced migraine, systemic administration of the FAAH inhibitor, URB597 attenuated nitroglycerin-induced mechanical hyperalgesia in mice and rats, indicating elevation of the AEA level by the FAAH inhibitors and a reduction in migraine pain." (PMID 35563056, 2022). "The specific distribution and homeostasis of endoCBs in the main regions of the nociceptive system and their generation ‘on demand’, along with recent availability of MAGL and FAAH inhibitors suggest new perspectives for endoCBs-mediated analgesia in migraine pain." (PMID 35457225, 2022). "The results support a role of AEA-mediated endocannabinoid signaling in migraine and suggest that FAAH may offer a new therapeutic option for the prevention of orofacial pain." (PMID 35563056, 2022). "Moreover, randomized clinical trials are needed to establish the therapeutic role of FAAH/MAGL inhibitors (or other ECS modulators) in migraine." (PMID 35329806, 2022). "Our results are consistent with the role of AEA-mediated endocannabinoid signaling in migraines and suggest that a FAAH inhibitor may offer a new therapeutic option for the prevention of orofacial pain." (PMID 35678693, 2022). "If proven, this could extend the therapeutic potential of MAGL/FAAH inhibition to migraine with aura." (PMID 35457225, 2022). "It should also be noted that the activity of MAGL and FAAH could be changed by oxidative stress and during neuroinflammation, conditions which contribute to migraine pathology." (PMID 35457225, 2022). "Future research efforts may focus on testing novel MAGL and FAAH inhibitors in in vivo models of migraine." (PMID 33530477, 2021). "Here, we demonstrated that the use of FAAH/MAGL inhibition may be a potential therapy for migraine pain, in particular, the modulation of spontaneous grooming behavior suggests a direct effect on regions implicated in trigeminal nociception." (PMID 34685523, 2021). "The findings provide further evidence in favor of a possible role of the endocannabinoid system in migraine pathophysiology but do not provide conclusive data regarding the specific importance of dual FAAH/MAGL inhibition as a potential migraine treatment versus single enzymatic inhibition." (PMID 34685523, 2021). "Interestingly, the inhibition of fatty acid amide hydrolase (FAAH) degrading AEA is also anti-nociceptive in migraine models." (PMID 29740328, 2018). "The human data and preclinical studies reviewed here confirm the importance of FAAH-regulated AEA signaling in the processing of nociceptive signals outside the CNS and specifically point to peripheral FAAH inhibition as a possible therapeutic opportunity for migraine pain." (PMID 29615860, 2018). "Additionally, some of these drugs allowed for the demonstration that peripherally specific FAAH inhibition may be an effective strategy to treat pain, including migraine." (PMID 37373250, 2023). "CNR2 and FAAH variants do not appear to be involved in migraine." (PMID 36605398, 2022). "Therefore, peripheral MAGL and FAAH inhibition may have a multicomponent effect on migraine and other types of inflammatory pain, mediated by mechanical hypersensitivity, and probably, neuropathic pain, which, like migraine, is characterized by allodynia." (PMID 33530477, 2021). "Thus, the enhancement and anti-nociceptive signaling of endoCBs, 2-AG and AEA, via MAGL and FAAH inhibition, can provide a beneficial reduction of the excessive cortical excitability and attenuate the central pain transmission in migraine and in inflammatory or neuropathic pain." (PMID 33530477, 2021).
migraine (continued). "Further support is found in a study involving FAAH and MAGL knockout mice using an NTG-induced mouse migraine model." (PMID 40630421, 2025). "Here, we tested in vivo the biological activity of the reversible dual AKU-005 FAAH/MAGL inhibitor, which showed potential anti-migraine activity in vitro." (PMID 38786051, 2024). "Increased anandamide levels via fatty acid amide hydrolase (FAAH) inhibition can decrease the pronociceptive responses and inflammatory mediators in animal models of migraine." (PMID 37373250, 2023). "Here, we profile the pharmacological activity of the FAAH inhibitor JZP327A, a chiral 1,3,4-oxadiazol-2(3H)-one compound, in the mediation of spontaneous and nocifensive behaviour in the animal models of migraine based on nitroglycerin (NTG) administration." (PMID 37373250, 2023). "FAAH inhibitors, such as the O-biphenyl-3-yl carbamate URB597, have been shown to produce anti-hyperalgesic effects in animal models of migraine." (PMID 35799128, 2022). "An efficient and specific MAGL and FAAH inhibition should prevent 2-AG and AEA hydrolysis, thereby increasing their levels in the nervous system and other migraine related tissues." (PMID 35457225, 2022). "The general FAAH inhibition by URB597, as well as the peripheral FAAH inhibition by URB937, reduced migraine related NTG-induced trigeminal hyperalgesia." (PMID 35457225, 2022). "In migraine-related cortex and cerebellum, we found the high activity of both MAGL and FAAH, suggesting a potential reserve for therapeutic interventions against the MAGL and FAAH activity by their specific inhibitors." (PMID 33530477, 2021). "In a preclinical model of migraine, both degradative enzymes (FAAH and MAGL) were increased in the mesencephalon, while only FAAH was increased in the medulla." (PMID 30202590, 2017). "The global FAAH inhibitor, URB597, as well as the peripherally restricted FAAH inhibitor, URB937, significantly inhibited nociceptive processing in nitroglycerine-induced migraine models." (PMID 41155546, 2025). "Indeed, several papers have demonstrated that the specific inhibition of FAAH or MAGL, the catabolic enzymes for AEA and 2-AG, respectively, counteracts the NTG-induced effects that are relevant to migraine." (PMID 38786051, 2024). "However, in the context of a distinct profile of MAGL and FAAH activity in areas involved in migraine pain signalling, MAGL prevails over FAAH in most of the areas with the exception of the meninges." (PMID 37038131, 2023). "Engaging the endocannabinoid system through inhibition of monoacylglycerol lipase (MAGL) and fatty acid amide hydrolase (FAAH), degrading endocannabinoids (endoCBs) 2-arachidonoylglycerol (2-AG) and anandamide (AEA), was proposed as a promising approach to ameliorate migraine pain." (PMID 37038131, 2023). "In the future, CBR antagonists and FAAH and MAGL enzyme inhibitors might be promising therapeutic targets in the treatment of both migraine and NP." (PMID 36835524, 2023). "One may, therefore, envisage that migraine pain can be treated by enhancing the levels of AEA and 2-AG by inhibiting its degrading serine hydrolases enzymes fatty acid amide hydrolase (FAAH) and monoacylglycerol lipase (MAGL), respectively." (PMID 37038131, 2023). "Our findings strongly support the benefit of dual MAGL/FAAH inhibition to ensure the most efficient analgesia via engagement of both main endoCBs, 2-AG and AEA, in various parts of the peripheral trigeminovascular system to treat migraine pain." (PMID 37038131, 2023). "More specifically, given the opposite activity profiles and dominant roles FAAH in meninges and MAGL in trigeminal ganglia, both areas involved in migraine nociception, we show that the combined inhibition of MAGL and FAAH enzymes to degrade 2-AG and AEA, respectively, has a greatly added benefit." (PMID 37038131, 2023).
migraine (continued). "The same group subsequently observed a significant reduction in FAAH and EMT activity in chronic migraine (CM) and medication overuse headache (MOH) sufferers, the latter being a complication resulting from the frequent use of medicines to treat migraine." (PMID 35329806, 2022). "Lending support to the present data, a prior study had shown that the dual FAAH/monoacylglyceride lipase (MGL) inhibitor, which simultaneously blocks the degradation of AEA and 2-AG, lowers serum levels of CGRP in the same animal model of migraine." (PMID 35799128, 2022). "Previous studies have demonstrated that modulation of the endocannabinoid system by selective inhibitors of the endocannabinoids’ catabolic enzymes—FAAH and MAGL—may represent a new therapeutic strategy for migraine." (PMID 34685523, 2021). "In particular, peripheral FAAH inhibition by URB937 increases the levels of AEA in trigeminal ganglia and reduces the trigeminal hyperalgesia induced by nitroglycerin (NTG) administration, used as an animal model of migraine." (PMID 34685523, 2021). "The authors conclude that inhibition of FAAH may be useful as a preventative treatment in migraine but not an abortive one." (PMID 40630421, 2025). "In a later study utilizing the same model, administration of the FAAH inhibitor URB597 before NTG administration significantly elevated levels of both AEA and PEA in the medulla, cervical spinal cord, and trigeminal ganglia, peripheral neural structures known to be involved in migraine pathology." (PMID 40630421, 2025). "This suggests that CBD’s anti-migraine effects may not be directly mediated by the inhibition of fatty acid amide hydrolase (FAAH), which is responsible for endocannabinoid breakdown." (PMID 38891938, 2024). "Both MAGL and FAAH activity and local 2-AG and AEA levels were measured by activity-based protein profiling (ABPP) and LC–MS/MS, respectively, in rat meninges obtained from hemiskulls of P38-P40 Wistar rats and human meninges from elderly patients undergoing non-migraine related neurosurgery." (PMID 37038131, 2023). "Peripheral and global inhibitors of fatty acid amide hydrolase (FAAH) – the enzyme that degrades anandamide (AEA), one of the best-known endocannabinoids—modulate the functional status of central structures and reduce gene expression of pain mediators in migraine-specific animal models." (PMID 37138206, 2023). "However, the activity of MAGL and FAAH and action of endoCB on spiking activity of meningeal afferents, from which migraine pain originates, has not been explored thus far." (PMID 37038131, 2023). "In this thematic review, we discuss how inhibition of the main endocannabinoid-degrading enzymes, monoacylglycerol lipase (MAGL) and fatty acid amide hydrolase (FAAH), could raise the level of endocannabinoids (endoCBs) such as 2-AG and anandamide in order to alleviate migraine pain." (PMID 35457225, 2022). "As such, peripherally restricted FAAH inhibitor URB937 presents analgesic effect in various animal models e.g., peripheral nerve injury (chronic sciatic nerve ligation, cisplatin-induced neuropathy), migraine (nitroglycerin-induced) arthritis (complete Freund’s adjuvant)." (PMID 35056095, 2021). "Given the overall prevalence of MAGL over FAAH in basal activity in most of the peripheral and central areas, we also investigated whether MAGL has a similar prevailing activity in certain areas of the PNS and CNS in comparison with a key migraine-related tissue such as TG." (PMID 33530477, 2021). "Therefore, by proposing MAGL and FAAH as main targets for an innovative multitarget (analgesic and antidepressant) treatment for migraine, we studied their activity in the rat PNS and CNS, in areas important for the generation and propagation of migraine-specific pain signals." (PMID 33530477, 2021).
migraine (continued). "Chronic CBD administration did not change FAAH gene expression induced by NTG administration, suggesting that CBD activity in our experimental setting is not directly mediated by the inhibition of AEA catabolism, and that anti-migraine effects could be associated with other mechanisms." (PMID 37138206, 2023). "Other recently published potent FAAH inhibitors include JNJ-1661010, AKU-009, AKU-010 and JZP327A, which have not yet been tested in migraine pathophysiology." (PMID 35457225, 2022). "Consistent with this, our study showed that in the cervical spinal cord, unlike other spinal cord areas, the activity of FAAH was not significantly different from MAGL, reflecting their specific role in migraine mechanisms." (PMID 33530477, 2021).